FTO (FTO alpha-ketoglutarate dependent dioxygenase)
Diseases named in the same sentence as FTO in open-access papers (continued):
Sharing a sentence is not in itself a finding about the gene and the disease.
tumor (continued). "Our findings are highly significant as they identify for the first time the tumor suppressive role of a small molecule inhibitor targeting FTO in solid tumors and establish a key pathway by which m6A modification mediates autophagic flux to modulate tumor progression." (PMID 36263177, 2022). "In addition, the elevated level of FTO in RCC was also confirmed in tumor tissues from our hospital." (PMID 35961973, 2022). "Furthermore, our results revealed that rapamycin-induced autophagy activation reduced FTO protein abundance, and FTO-mediated autophagy greatly promoted tumor progression including lung metastasis." (PMID 36263177, 2022). "FTO overexpression also significantly inhibited tumor growth and promoted EGR2 protein expression." (PMID 37529797, 2022). "FTO acts as a tumor suppressor to inhibit tumor glycolysis in PTC." (PMID 35090515, 2022). "Moreover, FTO plays critical roles in self-renewal and immune evasion of cancer stem cells, and small-molecule FTO inhibitors can exhibit strong anti-tumor effects in multiple types of cancer." (PMID 35064107, 2022). "Moreover, the small molecule inhibitor FB23-2 targeting FTO inhibited tumor growth in the PDX, suggesting that FTO is a potential therapeutic target for ccRCC." (PMID 36263177, 2022). "Previously, we found that the expression level of demethylase FTO was significantly higher in EC stem-like cells, and many studies have shown that the tumor stem cells could promote the development and metastasis of cancers." (PMID 35568876, 2022). "Moreover, R-2HG inhibits GBM tumor outgrowth and ameliorates tumor survival in vitro and in vivo by hindering FTO activity." (PMID 35864970, 2022). "Mechanistic studies showed that FTO played a pro-tumor role in vitro and in vivo." (PMID 35628623, 2022). "The hypothesis was that FTO may play distinct functions in various tumor types as part of a complex tumorigenesis mechanism." (PMID 35721711, 2022). "Mechanistically, FTO represses m6A modification of SLC1A5 mRNA and promotes its mRNA expression and translation, leading to increased glutamine uptake in RCC and enhanced tumor survival and progression, especially VHL-deficient cells." (PMID 36289851, 2022). "To determine whether FTO plays an anti-tumour role by inhibiting the expression of SNAI1 in EOC, we first established A2780 and OVCAR3 cell lines stably transfected with anti-FTO shRNA (sh-FTO) lentivirus." (PMID 36358640, 2022). "Collectively, FTO plays an important role in tumor progression and might be a potential therapeutic target in EC." (PMID 35568876, 2022). "In addition, the xenografts derived from TPC-1-Lv-FTO cells (FTO overexpression) demonstrated tumor weight and volume which were much lower than those extracted from TPC-1 vector (empty)." (PMID 35721711, 2022). "Regarding to m6A methylation, Zhuang and his colleagues find that m6A demethylase FTO could induce oxidative stress and ROS production and show impaired tumor growth." (PMID 35585886, 2022). "We found that FTO expression was reduced significantly in PCa tumor samples." (PMID 37529797, 2022). "Therefore, we detected the mRNA expression levels of demethylation genes ALKBH5 and FTO between tumor stem-like cells and their matching cell lines." (PMID 35568876, 2022). "Consequently, these results provide evidence that PDGFC overexpression is responsible for FTO-mediated tumor progression." (PMID 35422475, 2022). "For instance, ALKBH5 regulated Tregs and MDSC accumulation via modulating the expression of Mct4/Slc16a3; FTO facilitated immune invasion and desensitized tumor cells to T cell cytotoxicity; YTHDF1 was correlated with immune cell infiltration but attenuated DCs' cross-presentation capacity." (PMID 35936362, 2022). "In addition, FTO expression levels were inversely correlated with Wnt-3a levels in tumor tissues, further supporting the role of the activated Wnt/β-catenin signaling in the repression of FTO." (PMID 33966037, 2021).
tumor (continued). "Notably, the enhanced tumor growth and metastasis were abrogated by reconstituted expression of an RNAi-resistant (r) Flag-tagged FTO (rFTO) in H358 cells." (PMID 33966037, 2021). "Nevertheless, FTO deletion drastically inhibited tumor growth of As-T cells in mice." (PMID 33846348, 2021). "Our study revealed that FTO exerts a tumor suppressive effect on CRC invasiveness and metastasis, suggesting that FTO might be an important marker for predicting the recurrence and metastasis of CRC." (PMID 34218271, 2021). "Additionally, FTO overexpression correlates with tumour size, nuclear grade, peritumoral lymphovascular invasion, lymph node metastasis, and TNM stage." (PMID 34044876, 2021). "Meanwhile, knockdown of FTO decreased the expression of Ki67 by 64.6% in tumor tissues." (PMID 33634966, 2021). "Our findings identify the tumor suppressive role of FTO in CRC metastasis." (PMID 34218271, 2021). "As expected, only FTO showed lower protein expression in CRC tumor tissue." (PMID 34218271, 2021). "Besides the synthetic circRNAs-mediated anti-tumor Immunity, targeting FTO also contributes to anti-tumor Immunity." (PMID 33746967, 2021). "Taken together, the FTO exhibited a tumor-suppressive effect on BCa cells." (PMID 34499008, 2021). "FTO had the most significant difference with downregulation in paired tumor samples (p = 7.10E-19)." (PMID 34804948, 2021). "Also, the expression levels of YTHDC2, WTAP, and FTO were markedly lower in tumor tissues (p < 0.05)." (PMID 34277622, 2021). "We showed that FTO depletion-promoted tumor growth was blunted by c-Myc depletion." (PMID 33966037, 2021). "The cAMP pathway, as a target of FTO, is related to tumour inhibition." (PMID 34794452, 2021). "However, selective depletion of ‘FTO’ not only increases sensitivity to anti-PD-1 therapy but also increases m6A methylation-inhibition of critical pro-tumorigenic (tumor-promoting) genes." (PMID 34571899, 2021). "By contrast, a recent study uncovered a tumor suppressor function of FTO in ovarian CSC49." (PMID 33741917, 2021). "Correspondingly, FTO depletion resulted in increased glucose uptake, lactate production, cell proliferation, cell growth in soft agar, migration, and invasion of the tumor cells; these increases were all inhibited by c-Myc depletion." (PMID 33966037, 2021). "Inducible FTO knockdown decreased cell growth, tumor growth, and tumor weight." (PMID 33846348, 2021). "Growing evidence has demonstrated that m6A modification is closely associated with tumorigenesis, tumor differentiation, tumor proliferation, tumor invasion and worse survival in BC patients, including METTL3, METTL14, WTAP, ALKBH5, IGF2BP2, IGF2BP3, and FTO." (PMID 33926554, 2021). "Furthermore, histologic examination showed that FTO overexpression reduced MTA1 expression in tumor tissue." (PMID 34218271, 2021). "The tumor volume was significantly reduced in mice treated with FTO plasmid." (PMID 34499008, 2021). "Furthermore, we analyzed 113 stage III patients with paired tumor tissues and lymph node metastasis specimens and found that FTO expression was downregulated in lymph node metastasis tissue compared with the primary tumor." (PMID 34218271, 2021). "However, there is very little understanding of the regulation of tumor hypoxic microenvironment on FTO expression." (PMID 34218271, 2021). "In this study, to investigate the tumor-suppressive effects of FTO via m6A RNA methylation on BCa patients, a total of 15 cancer tissues and adjacent normal tissues (ANTs) were collected from BCa patients who received tumor resection in our hospital from September 2015 to December 2019." (PMID 34499008, 2021). "We also found that FTO-regulated AC026691.1 might function as an essential tumor suppression lncRNA in GC." (PMID 34399770, 2021).
tumor (continued). "Besides, the FTO expression was found as an independent prognostic factor for tumor grading (hazard ratio (HR) = 8.214, 95% confidence interval (CI): 1.517–5.028, P = 0.009) and OS rate (HR = 4.525, 95% CI: 2.285–6.133, P = 0.002) in BCa patients." (PMID 34499008, 2021). "Notably, the tumor tissue showed significantly higher expression levels of m6A regulators, except for FTO and ALKBH5, compared with the normal tissue with a P value <0.05." (PMID 33928026, 2021). "We found that the copy number loss of ZC3H13, FTO, YTHDC2, WTAP and ALKBH5 decreased the protein expression in tumor samples, and meanwhile, patients with amplification of IGF2BP3, HNRNPA2B1 and IGF2BP2 presented higher expression level of these three proteins than normal tissues." (PMID 32710725, 2020). "Furthermore, FTO promotes tumor cell proliferation, colony formation, and metastasis in breast cancer by mediating m6A demethylation in the 3′UTR of BNIP3 mRNA72." (PMID 32296573, 2020). "In addition, the protein expression levels of ALKBH5 and FTO in renal cancer tissues were significantly lower than those in normal kidney tissues and other tumor tissues." (PMID 32398132, 2020). "Given the inconsistent role of METTL3 and FTO in tumour progression, it is presumed that the discrepancy may be due to METTL3 and FTO acting on different downstream targets." (PMID 33029866, 2020). "Proteins from transplanted tumor tissues were extracted for Western blot analysis, and the results displayed that levels of FTO, MYC, CDK2, CDK4, Ki-67, PCNA and Bcl-2 proteins in miR-96 antagomir group were downregulated, while AMPKα2 and Bax proteins were raised." (PMID 33183350, 2020). "And two studies have reported ambiguous results about FTO, which may serve as either an oncogene or a tumor suppressor in HCC." (PMID 32772918, 2020). "A previous study discovered that the “writers” of m6A methylation, METTL3 and METTL14, could play both oncogenic and tumor suppressor roles in numerous cancers, while oncogenic roles have been reported for “erasers” such as FTO and ALKBH5." (PMID 31722709, 2019). "Moreover, in 88 patients with necrobiotic tumor, those with a lower expression of FTO also showed a poorer overall survival than those with a higher expression of FTO (p = 0.0273)." (PMID 31143705, 2019). "We found direct correlation of ALKBH3 and FTO expression with primary HNSCC tumor size." (PMID 31519943, 2019). "We found that silencing BNIP3 could significantly alleviate FTO-dependent tumor growth retardation in vitro and in vivo." (PMID 30922314, 2019). "Furthermore, forced overexpression of FTO in WM35 induced tumor growth in immunocompromised nude mice." (PMID 31239444, 2019). "BNIP3 dramatically alleviated FTO-dependent tumor growth retardation and metastasis." (PMID 30922314, 2019). "Although FTO’s functions or targets in various cancer subtypes are different, the oncogenic role of FTO can be attributed to two aspects, either promote oncogenes translation or trigger tumor suppressors’ transcripts decay, which is dependent on its demethylase activity." (PMID 31827395, 2019). "The correlation between increased FTO expression and tumour size may suggest a new regulatory role for this protein in tumour development." (PMID 31519943, 2019). "BNIP3 acted as tumor suppressor and alleviated FTO-dependent tumor growth and metastasis." (PMID 30922314, 2019). "Additionally, depletion of METTL3 or METTL14 enhances tumor tumorigenicity while FTO inhibitor treatment prevents tumor deterioration." (PMID 30062093, 2018). "Likewise, inhibition of the RNA demethylase FTO with its inhibitor MA2 reduced GSC-initiated tumor growth and prolonged the lifespan of GSC-grafted mice substantially." (PMID 30149601, 2018). "Moreover, inhibition of FTO suppresses tumor progression and prolongs lifespan of GSC-grafted mice substantially." (PMID 28297667, 2017).
tumor (continued). "SNP rs17817449 at 16q12/FTO showed an association with ER+ tumor with OR (95% CI) of 1.32 (1.09–1.60) but not with ER− or ER−/PR−/HER2− tumors." (PMID 23593120, 2013). "However there didn't seem to be any significant difference in tumor FTO expression in ER + vs ER-, PR+ vs PR- or Her2+ vs Her2- cancers." (PMID 21489227, 2011). "Furthermore, FTO may directly modify gene targets related to ferroptosis, thereby influencing tumor development." (PMID 40271153, 2025). "Thus, FTO-mediated demethylation of m6A on SLC6A11 mRNA to activate ferroptosis might be a tumor suppressor in PTC progression." (PMID 40819127, 2025). "In addition to ALKBH5, FTO is another m6A demethylase involved in tumor immunity." (PMID 41562066, 2025). "Additionally, animal studies confirmed the inhibitory effect of FTO knockdown on RB tumor growth." (PMID 41315216, 2025). "Therapeutically, targeting m6A regulators—such as through inhibition of METTL3 or FTO—disrupts tumor-intrinsic immune resistance and reshapes extrinsic immunosuppressive networks, thereby enhancing the efficacy of immune checkpoint inhibitors in cold tumor settings." (PMID 41050070, 2025). "Therefore, we next assumed whether Mupirocin regulates CRC ferroptosis and tumor growth through targeting FTO." (PMID 38600610, 2024). "We found that FTO-specific pharmacologic inhibitors FB23-2 and MA resulted in a similar of both apoptosis induction and proliferation inhibition in IDH1wt gliomaspheres, suggesting that FTO may be a critical target of D-2-HG whose inhibition can reduce tumor growth." (PMID 38445960, 2024). "Omeprazole-induced FTO inhibition enhances the activation of the mTORC1 signaling pathway and inhibits the pro-survival effect of autophagy, thereby increasing the antitumor efficacy of chemotherapeutic drugs in GC cells and leading to a synergistic tumor-suppressive effect." (PMID 39468015, 2024). "Similarly, upregulation of FTO mRNA and protein levels in human lung cancer tissues correlates with increased cell proliferation and tumor growth, while its downregulation leads to reduced proliferation and tumor growth." (PMID 38665783, 2024). "In addition, through subcutaneous tumorigenesis and IHC staining assays in nude mice, we found that downregulation of ARHGAP35 could reverse the inhibition of NPC tumor growth by promoting apoptosis in nude mice after combined knockout of FTO and ALKBH5." (PMID 38263362, 2024). "However, the FTO knockdown suppresses the tumor growth in HGC27 xenograft model." (PMID 39136000, 2024). "Intriguingly, the m6A demethylase FTO was found to preserve the transcription factors of bZIP family, including c-Jun, JunB and C/EBPβ, through its demethylation activity, thereby upregulating the expression of glycolytic genes in tumor cells and facilitating tumor progression." (PMID 37731821, 2023). "Moreover, given the fact that FTO posttranscriptionally modulates a large variety of target genes, either in a positive or negative way, participating in the cellular processes and determining the fate of tumor cells." (PMID 37919739, 2023). "However, recent studies showed that FTO acts as a tumor suppressor factor." (PMID 37437245, 2023). "Moreover, miRNA-binding sites were observed to overlap with areas rich in RRACH motifs, i.e., m6A binding sites, which led to the identification of specific tumour-suppressive RRACH binding miRNAs that facilitate FTO-dependent, transcript-specific demethylation." (PMID 36831575, 2023). "Additionally, tumor-intrinsic FTO could suppress the activation and effector states of CD8 + T cells." (PMID 36810281, 2023). "The upregulation or downregulation of FTO-related genes may affect the expression of some relevant oncogenes in tumor cells by affecting mRNA methylation; for example, chemokine CCL19 expression is downregulated in tumor tissues after the knockdown of FTO genes." (PMID 38053093, 2023). "Moreover, the tumor cell infiltration in NC was stronger than FTO knocked down in the spleen." (PMID 37402730, 2023).
tumor (continued). "Based on univariate Cox and LASSO regression, a risk model consisting of three high-risk genes (KIAA1429, RBM15, FTO) was established, and the expression difference between normal and tumor tissues of three genes was confirmed by immunohistochemical results of our clinical tissues." (PMID 36389678, 2022). "Moreover, knockdown of FTO retards tumor growth via induction of G0/G1 phase block." (PMID 35794625, 2022). "However, our study and results supported that FTO mainly had the anti-tumor activity in LUAD." (PMID 35945194, 2022). "Similarly, inhibition of FTO can reduce tumor resistance to PD-1 therapy." (PMID 35590394, 2022). "Hence, FTO plays a critical role in promoting PDAC tumor growth." (PMID 35422475, 2022). "Moreover, the results of the two studies on FTO remain unclear; FTO may serve as an oncogene or a tumour suppressor gene in HCC." (PMID 36434140, 2022). "Moreover, FTO silencing reduced mRNA levels of ZEB1 in SN-exo-cultured tumor cells." (PMID 36302751, 2022). "In addition, FTO represses T cell immune activation in the lung cancer cell lines and melanoma cells by regulating JunB and C/EBPb in an m6A-dependent way to accelerate tumor glycolysis." (PMID 35720276, 2022). "Furthermore, FTO overexpression inhibited PCa tumor growth and EGR2 expression in vivo." (PMID 37529797, 2022). "As a result, these findings suggest that FTO may function as a PTC tumor suppressor." (PMID 35721711, 2022). "The xenografts experiment in nude mice further demonstrated that ablation of LINC00022 completely mitigated FTO-induced cell proliferation of KYSE70 in vivo, whereas over-expression of FTO partially relieved the inhibitory effect of tumor formation caused by LINC00022 knockdown." (PMID 34544449, 2021). "In addition, the tumor inhibitory rate was higher in mice in the FTO plasmid group." (PMID 34499008, 2021). "However, simultaneously overexpress PYCR1 promoted FTO-depleted tumor growth." (PMID 33461172, 2021). "Therefore, FTO may play a potential role in managing immune evasion and sensitizing tumor cell to T cell cytotoxicity by m6A-dependent mechanism." (PMID 33779704, 2021). "However, decreased FTO expression in the tumor shown in our study was in contrast to its results." (PMID 34149936, 2021). "Therefore, FTO is not only a tumour suppressor but also a potential indicator of ovarian function." (PMID 34794452, 2021). "Therefore, FTO acts as a tumor promoter in the progression of ESCC." (PMID 34376206, 2021). "Furthermore, METTL14 knockdown partially reversed the effect of FTO deletion on tumor growth." (PMID 33846348, 2021). "Furthermore, through the establishment of a xenograft mice model by injecting FTO‐knockdown 253J cells, we observed on day 33 after cell implantation that tumor growth (p < 0.001) and tumor weight were significantly decreased, by 48.7% and 51.2%, respectively (p < 0.05)." (PMID 33634966, 2021). "In addition, the effects of ALKBH5 on carcinogenesis might relate to the stage of tumor and the different downstream molecules as shown by other epitranscriptomics enzyme such as FTO." (PMID 34112124, 2021). "Moreover, FTO could promote tumor progression by regulating multiple signaling pathways in a variety of tumors." (PMID 33718213, 2021). "The authors have further identified a small molecule inhibitor of FTO, R-2HG, which decreases the proliferation and survival of tumor cells, thus suggesting that targeting m6A demethylases may be an effective therapeutic strategy for treating AML and possibly other cancers." (PMID 32296573, 2020). "However, mechanistic action of FTO or ALKBH5 for tumor formation remains to be identified." (PMID 33511112, 2020). "However, in the present study, we showed that FTO functions as a tumor suppressor in ICC, which implies that FTO may be a context-dependent regulator in oncogenesis network." (PMID 31143705, 2019). "Thus, the content of ALKBH3 and FTO increases along with the tumour size." (PMID 31519943, 2019).